INS (insulin)
Diseases named in the same sentence as INS in open-access papers (continued):
Sharing a sentence is not in itself a finding about the gene and the disease.
diabetes (continued). "Gelam honey exerts protective effects against diabetes and hyperglycemia-induced oxidative stress through improving insulin content and insulin resistance by producing the differential expression of insulin signaling pathways MAPK, NF-κB, IRS-1 (ser307) and Akt in HIT-T15 cells." (PMID 33435215, 2021). "The cost of insulin accounts for 70% of the total cost of diabetes treatment." (PMID 34383816, 2021). "Excluding statin users and individuals with diabetes showed similar associations for triglycerides, HbA1c, insulin, and HOMA-IR, though the associations were no longer significant in the adjusted model." (PMID 34886380, 2021). "Thus, better knowledge regarding how the use of insulin as an anabolic agent influences skeletal tissues greatly needed in view of patients with diabetes." (PMID 34200167, 2021). "The intervention of conjugated estrogens could protect postmenopausal women from diabetes by promoting the degradation of misfolded proteins during insulin synthesis in β cells." (PMID 34571259, 2021). "This glucose-lowering effect of these flavonols was suggested to be contributed by their ability to improve insulin release via their antioxidative effects on pancreatic β-cells, which protect them against further hyperglycemia-induced destruction in type 1 diabetes mellitus." (PMID 34065781, 2021). "Interestingly, insulin therapy and other diabetes drugs (such as SGLT2 inhibitors) have been suggested to suppress the production of hepcidin and modulate iron homeostasis, thereby increasing erythropoiesis and hematocrit." (PMID 34222290, 2021). "According to Diabetes Poland, children and adolescents with T1DM should be treated with intensive insulin therapy, and use continuous glucose monitoring (CGM) systems from the onset of the disease to improve the metabolic control of diabetes, and decrease the risk of acute and chronic complications." (PMID 34836071, 2021). "In the case of sufficient secretion, improving insulin sensitivity is a good way to treat diabetes." (PMID 33663083, 2021). "Insulin should be used to treat diabetes in patients with COVID-19." (PMID 34650947, 2021). "Therefore, GNPs can be potentially applied as the carrier to extend insulin activity for reducing the frequency of insulin injection in diabetes mellitus." (PMID 34572503, 2021). "Inflammation can alter insulin action and give rise to diabetes and obesity by blocking insulin receptor downstream events, impairing insulin receptor substrate 1 (IRS-1) activation and phosphatidylinositol 3-kinase-dependent (PI3K) pathways, therefore compromising insulin signaling." (PMID 33430045, 2021). "For example, a patient wishing to receive diabetes education for insulin management would need to visit a diabetes education clinic with data from their glucometers to show a registered nurse (RN), dietician, or physician so that they are able to receive the necessary support from their providers." (PMID 34683005, 2021). "The increased death rate in patients undergoing insulin treatment may be correlated with advanced stage of diabetes." (PMID 34256824, 2021). "Diabetes involves metabolic alterations, hormonal imbalances particularly of insulin/insulin growth factor-1 and adiponectin/ leptin, and immune response such as elevated levels of pro-inflammatory cytokines like tumor necrosis factor-a (TNF-α), and all these features it shares with cancer." (PMID 34225729, 2021). "The insulin-responsive GLUT4 plays a crucial role in insulin-mediated facilitated glucose uptake into adipose tissue and muscle, and impaired expression of GLUT4 has been linked to obesity and diabetes." (PMID 33926085, 2021). "Besides, insulin, one of the potent anti-diabetes dietary supplements, was found to promote Bacteroides, Lachnospiraceae, and Phascolarctobacterium, in the diabetic mouse." (PMID 33924088, 2021).
diabetes (continued). "In turn, signal transmission from deteriorating retinal neurons together with elevated glucose, diminished insulin, and variations in the circulating lipids, lipoproteins, and proteins collectively may damage the vascular tissue at later stages of diabetes." (PMID 35046899, 2021). "Moreover, most individuals with diabetes were being treated with metformin (75.0%), only 6.7% were taking insulin and 34.5% were taking other oral medications for diabetes (alone or in combination with metformin or insulin)." (PMID 34676236, 2021). "Understanding the specific factors that underlie β-cell loss in these diseases may lead to new approaches to maintain insulin secretion and thereby treat or cure diabetes." (PMID 34822454, 2021). "Furthermore, microneedles is a kind of continuous administration, so that it can reduce the frequency of administration, especially for insulin injection in patients with diabetes." (PMID 34641460, 2021). "To investigate whether the metabolism of offspring was affected by uterine environment or oocytes of maternal diabetes, we analyzed glucose tolerance and insulin tolerance in all the three F1 cohorts when they were 16 weeks old." (PMID 34381787, 2021). "Lysosomal trafficking and autophagy in the beta cell may be a possible mechanism of insulin secretory defects in diabetes, with a recent study providing evidence for impairment of lysosomal function in human T1D." (PMID 34659118, 2021). "The following factors contribute to the improved incidence of T2DM and the ethnic-specific character of East Asians, insulin secretion, rising BMI, stress, a proclivity for visceral fat, decreased pancreatic β-cell mass, diabetes onset at an early age, and cardiac events." (PMID 34822452, 2021). "Furthermore, some trials have demonstrated structured diabetes control programs achieving targeted glycemic control by using daily blood glucose monitoring results as a basis to self-adjust insulin dose in poorly or uncontrolled type 2 diabetes patients." (PMID 34704954, 2021). "Metformin or insulin treatment could ameliorate symptoms of diabetes and partly recover the abnormal biochemical indicators." (PMID 35046817, 2021). "All subjects met at least one of the following criteria: inability to perform > 4 METs by history (62%), insulin-treated diabetes mellitus (53%), serum creatinine > 1.72 mg/dL (8%), history of MI, PCI or CABG (5%), stable angina (3%), cerebrovascular disease (1%), peripheral vascular disease (1%)." (PMID 32394403, 2021). "Overall, these studies support the hypothesis that SCs can be engineered to deliver therapeutic proteins, like insulin, to treat chronic diseases, like diabetes." (PMID 33800470, 2021). "However, as testosterone levels are affected by diabetes and insulin levels, adjusting the findings with diabetes biomarkers are therefore necessary to avoid confounders and risk of bias." (PMID 33477418, 2021). "SC‐islets could secrete insulin in response to glucose and prevent diabetes once transplanted into mice." (PMID 34155834, 2021). "Deletion of Pdx1 in β-cells induces insulin-secretion disorders and diabetes." (PMID 34066196, 2021). "An implication of this finding is that separate insulin allows for more mealtime flexibility over mixed insulin and hence may be suitable for Type 1 diabetes mellitus patients in Tanzania who have been shown to have problems with regular meals." (PMID 33855206, 2021). "However, it is important to underline that the poorer outcomes are probably due to the fact that use of insulin reflects more advanced diabetes and patients who are often older and frailer." (PMID 34031865, 2021). "Therefore, our study is more likely to be applicable to T2DM patients, while guidance for insulin treatment in COVID-19 patients with different types of diabetes, especially T1DM, needs more clinical research." (PMID 34367067, 2021).
diabetes (continued). "With respect to IR, the levels of methionine transmethylation were lower in insulin resistant patients with hepatic steatosis, while methionine restriction has consistently been shown to increase hepatic insulin sensitivity and protect against diabetes and metabolic dysfunction in rodents." (PMID 34046015, 2021). "Therefore, taken together, we concluded that diabetes or insulin signaling pathway is interacting or sharing the sub-pathways with pro-inflammatory cytokine signaling cascades (TLR, Fc epsilon receptor, FoxO, and HIF-1) associated with COVID-19 pathogenesis." (PMID 34067609, 2021). "Moreover, sacubitril-valsartan is superior to enalapril in reducing HbA1c values and lowering the rate of initiation of insulin therapy over three years in patients with both diabetes and HFrEF." (PMID 34740359, 2021). "Diabetes mellitus (DM) is a metabolic disorder characterized by chronic hyperglycemia with impaired carbohydrate, fat and protein metabolism and resulted from either inadequate insulin secretion, resistance to the action of insulin or both." (PMID 33556090, 2021). "Varying levels of transgenic insulin expression in the thymus may influence the diabetes progression in NOD mice." (PMID 33841427, 2021). "Besides, Individuals with earlier age at diagnosis of diabetes have higher percentage of insulin-user, while lipid-lowering treatment and antihypertensive drugs are less used (all P for trend < 0.05)." (PMID 34671316, 2021). "Due to the dramatic differences that exist in the phenotypes exhibited by these models of diabetes, it remains to be determined whether the hypocarnitinemia is due to chronic hyperglycemia, defective insulin signaling, or systemic inflammation." (PMID 34833964, 2021). "The severity of DM: The severity of diabetes might be reflected by antidiabetic agents or insulin to control hyperglycemia." (PMID 34873559, 2021). "In addition, deep brain stimulation was further shown to enhance peripheral insulin sensitivity in humans with diabetes." (PMID 33974562, 2021). "In addition, angiotensin II also interferes with the anti-inflammatory action of insulin, which highlights its deleterious effect in patients with diabetes." (PMID 34710053, 2021). "Insulin was shown to influence both protein and lipid metabolism in the inner ear, although the mechanisms underlying the association between diabetes and inner ear dysfunction are not yet known." (PMID 34680948, 2021). "Moreover, polyphenols help prevent diabetes by inhibiting glucose absorption in the intestine, increasing insulin secretion in the pancreas, improving glucose absorption in muscle and adipose cells, and inhibiting glucose release from the liver." (PMID 33572166, 2021). "The heterogeneity of the results depending on the type of diabetes, the type of insulin treatment or control of the disease may also depend on whether the sample is collected under fasting or non-fasting conditions." (PMID 33800850, 2021). "Among 2712 subjects with diabetes, 2171 were treated with oral hypoglycemic agents or insulin." (PMID 33845772, 2021). "In this study, we identify BBR as a glucose-dependent insulin secretagogue for treating diabetes without causing hypoglycemia that targets KCNH6 channels." (PMID 34556670, 2021). "Diabetes results from a decreased glucose uptake into insulin-sensitive tissues." (PMID 34497520, 2021). "Type 1 Diabetes Mellitus (T1D), a paradigmatic case, is a disease caused by a lack of insulin which generates persistent hyperglycemia and energy wasting." (PMID 33672506, 2021). "Diabetes mellitus treatments are focused on improving insulin secretion." (PMID 33572166, 2021). "All of a sudden, with the appearance of insulin, people with diabetes were living." (PMID 34762125, 2021).
diabetes (continued). "General management of diabetes is defined by eating a healthy, nutritious diet, avoiding sugar‐rich food, maintaining a balanced weight, exercising in a regular manner, taking medications regularly and, if needed, taking insulin therapy." (PMID 34925813, 2021). "KD has helped patients with diabetes reduce their HbA1c and reduce the need for insulin." (PMID 34068325, 2021). "Based on the findings, FHL and diabetes-specific quantitative skills influenced the patients’ health outcomes (e.g., the existence of diabetes-related complications) and impacted their diabetes self-care activities such as the daily blood glucose testing or daily insulin administration." (PMID 33561956, 2021). "Our results show that metformin improved dysglycemia and insulin sensitivity, independent of weight loss, in a young population with prediabetes/diabetes and psychosis spectrum illness, that is at extremely high risk of early cardiovascular mortality." (PMID 33854039, 2021). "These determinant factors were the presence of regular follow-up in the diabetic clinic, received diabetic education, alcohol drinking, discontinuation of medications (insulin and oral hypoglycemic agents), presence of comorbidities, and type of diabetes mellitus." (PMID 33602195, 2021). "However, in Japan, there has been no previous report of the effectiveness bariatric surgery in a case of morbid obesity associated with acute onset type 1 diabetes mellitus (T1DM), in which pancreatic β-cells were destroyed and endogenous insulin was depleted." (PMID 33409743, 2021). "Based on the current evidence, resveratrol may improve insulin resistance, lower fasting blood glucose and insulin levels, and improve oxidative stress in patients with type 2 diabetes mellitus." (PMID 34484395, 2021). "Insulin-resistant morbidly obese subjects have a different DNA methylation pattern in visceral adipose tissue, compared to insulin-sensitive ones, resulting in close to a 10% difference in diabetes-related expressed genes." (PMID 34829720, 2021). "Mismatch of the insulin pen and cartridge is not uncommon and is a potential risk for individuals with diabetes due to serious consequences associated with incorrect insulin usage." (PMID 34924015, 2021). "However, at the same time, UCP2 inhibits insulin secretion, which is manifested as an elevated content of ucp2 mRNA in rats with alloxan-induced diabetes vs. the diabetic group treated with SkQ1." (PMID 34829620, 2021). "Most cases of diabetes include several genes, each of which contributes to an increased risk of type 2 diabetes, and similar genes related to T2DM poorly show recognized pathways of insulin signaling." (PMID 35046895, 2021). "In addition, insulin preparations and metformin had high odds of coprescription, which is in line with studies showing that ADHD is associated with both obesity and diabetes." (PMID 32478603, 2021). "An intelligent insulin delivery system is highly desirable for diabetes management." (PMID 35056918, 2021). "Diabetes is defined clinically by a fasting blood glucose value of >7 mM, or fasting HbA1c level >6.5%, predominantly due to peripheral insulin resistance (type 2 diabetes; T2D) or insufficient pancreatic insulin production (type 1 diabetes; T1D)." (PMID 34113491, 2021). "We can describe diabetes as a disease of insulin insufficiency or impaired insulin action." (PMID 34319011, 2021). "The investigators speculated that the decline in diabetes-associated mortality over the years was due to increased OGTT screening resulting in earlier diagnosis and more aggressive treatment with insulin." (PMID 34926166, 2021). "Several peptides with antidiabetic potential have been identified that could decrease blood glucose level, improve insulin uptake and inhibit key enzymes involved in the development and progression of diabetes." (PMID 34445765, 2021).
diabetes (continued). "Our objective is to assess whether automated insulin delivery can improve glycaemic control and alleviate the burden of diabetes management in this particular age group." (PMID 33579766, 2021). "Diabetes drugs may have indirect effects on the brain by affecting circulating concentrations of insulin and glucose." (PMID 34676236, 2021). "Following insulin treatment, the diabetes-induced changes of NOXs were significantly reversed." (PMID 33664862, 2021). "Additionally, hypersecretion of somatostatin can disable the counter-regulatory glucagon secretion during insulin-induced hypoglycemia in diabetes." (PMID 33494193, 2021). "Insulin is susceptible to in vivo glycation by d-ribose and reactive carbonyls, as MG, especially in diabetic conditions and AGE species are considered the main responsible for diabetes-related vascular complications." (PMID 34356360, 2021). "Currently, T1D research consortium TrialNet screens first-degree relatives of individuals with T1D for islet autoantibodies against insulin, GAD65, IA-2, ICA512, and ZNT8 autoantigens; positivity for two or more of these specificities confers an ~80% risk of developing diabetes within 20 years." (PMID 33418839, 2021). "In fact, it cannot be ascertained whether this effect is attributable to the mitogenic stimulus of insulin on tumor cells or reflects the severity of diabetes and the difficulty to treat hyperglycemia with oral agents." (PMID 33467038, 2021). "Moreover, other risk factors, such as obesity, antidiabetic drug therapies such as intake of exogenous insulin in type 1 diabetes, duration of the diabetes also influence the outcomes." (PMID 34535145, 2021). "Interestingly, the monomeric structure of this insulin has been used to design a small and fully active insulin analog to treat human diabetes." (PMID 34564647, 2021). "The mean dose of prescribed insulin decreased by 81% and the diabetes reversal increased to 53.5%." (PMID 34068325, 2021). "Diabetes Mellitus is a group of metabolic disorders with various etiologies that are defined by elevated serum glucose levels or persistent hyperglycemia, resulting in abnormalities of insulin secretion, insulin action, or both." (PMID 34584998, 2021). "Insulin secreted by pancreatic beta cells regulates storage and usage of nutrients, and its relative or absolute lack results in diabetes mellitus that affects more than 460 million people around the world, a number that is expected to increase to 700 million by 2045." (PMID 34359828, 2021). "ESC-derived insulin-producing tissue alleviated diabetes in mice." (PMID 34255619, 2021). "Diabetes, but not insulin sensitivity, was particularly associated with the features of the deep lower abdomen." (PMID 34591793, 2021). "The diabetes was getting worse and they were saying about having take insulin." (PMID 34120310, 2021). "Another study also reported that 8.3% people suffer from DM to date with the number predicted to increase to more than 700 million globally by 2045.2-4 Apart from the use of insulin or oral hypoglycemic, other effective methods for treating diabetes have yet to be developed." (PMID 33747864, 2021). "Diabetes Mellitus (DM), defined as a group of metabolic diseases characterized by hyperglycemia, resulting from defects in insulin secretion, action or both, is a multifactorial chronic disease that became a worldwide concern because of its epidemic proportions and complex management." (PMID 33535510, 2021). "In addition, the downregulation of DsbA-L expression reduces PPARγ agonist function, suggesting that DsbA-L not only increases insulin sensitivity, but also has a prominent function in the prevention of diabetes." (PMID 34906241, 2021). "The influence of the physician–industry financial relationship on clinical practice for diabetes care involving insulin has been of great concern under the regulating system for pharmaceutical manufactures setting insulin prices and direct competition in the insulin market." (PMID 34061852, 2021).